STK11 (serine/threonine kinase 11)
Diseases named in the same sentence as STK11 in open-access papers (continued):
Sharing a sentence is not in itself a finding about the gene and the disease.
Peutz-Jeghers syndrome (continued). "Peutz-Jeghers syndrome (PJS) is a hereditary cancer-prone disorder linked to mutation of LKB1 (also known as Serine/Threonine Protein Kinase 11; STK11)." (PMID 22916036, 2012). "Peutz-Jeghers syndrome (PJS) is caused by mutations in the tumor suppressor gene, STK11, and is characterized by gastrointestinal hamartomas, melanin spots on the lips, and an increased risk of developing cancer." (PMID 22168747, 2011). "It is worth noting that STK11, found to be copy-number lost in 30% of this subgroup, has been identified as a large-scale deletion in a patient with schizophrenia and Peutz-Jeghers syndrome." (PMID 20064257, 2010). "The tumor also lacked STK11 mutations, arguing against STK11-related adnexal tumors, which are typically high-grade, aggressive, and associated with Peutz-Jeghers syndrome." (PMID 40959354, 2025). "We utilized as much pertinent research as we could find using the medical subject heading phrases "Peutz Jeghers syndrome", "tumor biomarkers", "chromosome 19p13.3", and "STK11/LKB1 gene" as well as various word combinations." (PMID 38800180, 2024). "Second, the presence of STK11/LKB1 germline mutations, which are specific for Peutz-Jeghers syndrome, was not investigated in solitary PJP patients." (PMID 31582972, 2019). "STK11 is a tumor-suppressor gene involved in causing Peutz Jeghers syndrome, but the role of STK11/LKB1 gene inactivation in neoplasia has not been conclusively demonstrated so far." (PMID 31775759, 2019). "Increased risk of endometrial cancer caused by mutation in the phosphatase and tensin homolog (PTEN) gene in Cowden syndrome (CS) is also demonstrated, as well as ovarian, uterine and cervical cancers related to Peutz-Jeghers syndrome (PJS), due to liver kinase b1 (LKB1/STK11) gene mutation." (PMID 26337050, 2015). "Furthermore, the diagnosis of pancreatic ACC was made in a 46-year-old male affected with liposarcoma, polyps and hamartomas of the colon, who carried a germline mutation in STK11/LKB, the gene causing the Peutz-Jeghers syndrome." (PMID 23374397, 2013). "Similar observations were made for the LKB1 gene (also known as STK11), responsible for Peutz-Jeghers syndrome (PJS; OMIM 175200), an autosomal dominant predisposition to hamartomas (polyps of the GI tract with a pronounced mesenchymal component, very similar to those characteristic of JPS)." (PMID 19014666, 2008). "LKB1 (also called STK11) is a tumor suppressor gene in Peutz-Jeghers syndrome." (PMID 19099607, 2008). "Peutz-Jeghers syndrome (PJS) is a rare hereditary disorder characterized by gastrointestinal (GI) hamartomatous polyps, due to mutation of the STK11/LKB1 gene located on chromosome 19p." (PMID 39098175, 2024). "So far, no STK11 pathogenic variants for Peutz-Jeghers syndrome have been identified in TUMOSPEC." (PMID 34359559, 2021). "We conclude that reported mutations in the STK11 gene are not responsible for Peutz- Jeghers syndrome in Indian patients, but novel mutations too, may not explain the disease in majority of them." (PMID 17010210, 2006). "STK11/LKB1 was first discovered and recognized as an important tumor suppressor gene in the 1990s after analyzing the genomic sequence of patients with Peutz-Jeghers syndrome." (PMID 35165542, 2022). "Peutz-Jeghers syndrome (PJS) is a rare disease due to the malfunction of LKB1 (STK11) gene." (PMID 32799895, 2020). "Liver kinase B1 (LKB1), also known as serine/threonine kinase 11 (STK11), was originally identified as a susceptibility gene of Peutz-Jeghers syndrome (PJS), an inherited disorder characterized by gastrointestinal tract polyps and predisposition to developing cancers." (PMID 27705915, 2016).
Peutz-Jeghers syndrome (continued). "STK11 was identified in 1998 as a novel tumor suppressor gene in patients with Peutz-Jeghers syndrome (PJS), an autosomal, dominant disorder characterized by the presence of pigmented macules on the skin and mouth, coupled with the growth of benign polyps in the gastrointestinal tract." (PMID 24280377, 2013). "Studies could not find somatic mutation in STK11/LKB1 locus on chromosome 19p which is responsible for Peutz-Jeghers syndrome (PJS) and only the LOH of this tumor suppressor locus was determined in BC samples." (PMID 24312913, 2013). "The tumor suppressor serine-threonine kinase LKB1, also referred to as STK11, is responsible for Peutz-Jeghers Syndrome (PJS), an autosomal-dominant disorder characterized by mucocutaneous hyper-pigmentation and benign gastrointestinal hamartomatous polyps and is attributed to mutations in LKB1." (PMID 23451056, 2013). "STK11 testing that is for Peutz-Jeghers syndrome was negative." (PMID 39119533, 2024). "Liver kinase B1(LKB1), also known as serine/threonine kinase 11(STK11), is the tumor suppressor gene found for the first time in patients with Peutz-Jeghers syndrome (PJS)." (PMID 28813465, 2017). "Germline mutations or large-scale deletions in the coding region and splice sites of STK11/LKB1 do not account for all cases of Peutz-Jeghers syndrome (PJS)." (PMID 15774015, 2005).
non-small cell lung carcinoma (153 papers, 2008 to 2026). A group of at least three distinct histological types of lung cancer, including non-small cell squamous cell carcinoma, adenocarcinoma, and large cell carcinoma. "For example, somatic loss-of-function variants in STK11 are found in >20% of non-small cell lung cancer (NSCLC) patients, where they are associated with poorer prognosis and resistance to immunotherapy." (PMID 40791513, 2025). "In KRAS-mutant non-small cell lung cancer, STK11 co-mutations are linked to reduced CD8+ T-cell infiltration and diminished PD-L1 expression." (PMID 41170373, 2025). "As an example of these dynamics, we find STK11, a multifunctional gene that acts as a tumor suppressor in non-small cell lung cancers, is highly mutated and its expression is reduced by about 50%." (PMID 38704802, 2024). "In the proportion of non-small cell lung cancer patients that have STK11-inactivating mutations, this LKB1 deficiency increases cytotoxicity of ERK inhibitors." (PMID 39594681, 2024). "Here, we identify a dexamethasone-GR mediated anti-cancer response in a subset of aggressive non-small cell lung cancers (NSCLCs) that harbor Serine/Threonine Kinase 11 (STK11/LKB1) mutations." (PMID 37035141, 2023). "Almost 40% of LCNECs have molecular alterations often identified in non-small cell lung cancer (STK11, and KEAP1 mutations) with high expression of ASCL1 and neuroendocrine markers (defined as type I LCNEC)." (PMID 36553576, 2022). "STK11, mutated or deleted in a third of non-small-cell lung cancer patients, fosters an immunologically “cold” tumor microenvironment, with minimal penetration of tumors by T cells, rendering anti-PD1/PDL1 drugs ineffective." (PMID 33178836, 2020). "Inactivating STK11 mutations have recently emerged as a putative mechanism of resistance to PD-1 inhibitors in non-small cell lung cancer (NSCLC)." (PMID 32158697, 2020). "In a mouse model of KRAS-driven non-small cell lung cancer, STK11/LKB1 loss was found to affect the immune microenvironment." (PMID 31775797, 2019). "A mouse model of non-small cell lung cancer tumors with LKB1 (gene expression product of STK11) and KRAS mutation showed specific response to phenformin." (PMID 26431491, 2015). "Additionally, sporadic malignancies such endometrial carcinoma, pancreatic, cervical, and non-small-cell lung cancer have been linked to STK11 mutations." (PMID 40171220, 2025). "Indeed, somatic loss-of-function mutations in the gene encoding LKB1 (STK11) occur in approximately 30% of non-small-cell lung cancers and 20% of cervical cancers." (PMID 24467442, 2014). "More KEAP1 mutations were also present in CS1 and CS4; studies have shown that non-small cell lung cancer (NSCLC) patients carrying STK11/KEAP1 mutations have less immune cell infiltration, which may lead to a poorer response to immune checkpoint inhibitors (ICIs) or poorer survival." (PMID 35721082, 2022). "Liver kinase B1 (LKB1, encoded by STK11) is an important tumour suppressor, with approximately 30% of non-small cell lung cancer (NSCLC) patients harbouring LKB1 mutations." (PMID 42157939, 2026). "In non-small cell lung cancer, STK11/LKB1 mutation is associated with a shorter OS compared with wild-type." (PMID 38366663, 2024). "The Kirsten rat sarcoma viral oncogene homolog (KRAS) and serine/threonine kinase 11 (STK11) co-mutations are associated with the diverse phenotypic and heterogeneous oncogenic subtypes in non-small cell lung cancer (NSCLC)." (PMID 37373999, 2023).
non-small cell lung carcinoma (continued). "In non-small-cell lung cancer (NSCLC), concurrent mutations in the oncogene KRAS and tumor suppressor STK11 (also known as LKB1) confer an aggressive malignant phenotype, an unfavourability towards immunotherapy, and overall poor prognoses in patients." (PMID 35011738, 2022). "Liver kinase B1 (LKB1; also known as STK11) is frequently mutated in non-small-cell lung carcinomas (15–35%) and cervical carcinomas (20%)." (PMID 36294681, 2022). "Somatic mutations in SMARCA4 and/or BRG1 (Brahma-related gene 1) loss are present in a subset of non-small cell lung carcinomas with distinct morphological features, harboring less EGFR mutations, but more KRAS, STK11, and KEAP1 mutations." (PMID 36371186, 2022). "Mutation in the tumor suppressor gene STK11, which regulates cell proliferation, was shown to be a negative immunotherapy predictor in non-small cell lung carcinoma (NSCLC) patients, and STK11 mutations were associated with worse survival than those without mutations." (PMID 35145511, 2021). "Activation of KRAS signaling along with homozygous deletion of LKB1 (also known as STK11 or serine/threonine kinase 11) promoted cancer progression and metastasis in non-small cell lung cancer models." (PMID 31681559, 2019). "STK11 mutations are associated with primary resistance to PD-1/PD-L1 agents in non-small cell lung cancer; however, their role in metastatic gastric cancer has not been well established." (PMID 36145703, 2022). "Recently, a comprehensive study in non-small cell lung cancer demonstrated that reduction in STAT3 in the tumor microenvironment using an antisense oligonucleotide reversed immunotherapy resistance in preclinical STK11 knockout mouse models." (PMID 35267462, 2022). "Mutations in STK11 (STK11Mut) gene may present a negative impact on survival in Non-small Cell Lung Cancer (NSCLC) patients, however, its relationship with immune related genes remains unclear." (PMID 38736875, 2024). "For example, a recent study identified that alterations in STK11/LKB1 and/or KEAP1 enhance the antitumor activity of ATR inhibitors in non-small cell lung cancer in vitro and in vivo." (PMID 41614897, 2026). "A carcinoid subtype in which SMARCA4, KRAS, FGF3/4/19, STK11, CDKN2A/B, and other genomic alterations predominate in non-small cell lung cancer-like subtypes." (PMID 40661782, 2025). "This review describes the mechanisms of targeted-drug resistance and newly identified non-small cell lung cancer targets (e.g., KRAS G12C, NGRs, DDRs, CLIP1-LTK, PELP1, STK11/LKB1, NFE2L2/KEAP1, RICTOR, PTEN, RASGRF1, LINE-1, and SphK1)." (PMID 36909198, 2023). "Gene mutations are often involved in tumorigenesis, the clustered deletions were found in ABL1, NOTCH1, RET, STK11, GNA11, and JAK3 genes in CRC, melanoma, and non-small cell lung cancers." (PMID 32850446, 2020). "Moreover, smoking-related non-small cell lung cancer (NSCLC) mutations, including STK11, KEAP1 and KRAS, are not uncommon." (PMID 38347129, 2024).
non-small cell lung carcinoma (continued). "In addition, among non-small cell lung cancer patients, KEAP1 and STK11 mutated patients are not sensitive to immunotherapy and have shorter disease-free and overall survival." (PMID 37973895, 2023).
melanoma (80 papers, 2009 to 2025). A malignant, usually aggressive tumor composed of atypical, neoplastic melanocytes. "For example, a likely pathogenic mutation of the Peutz‐Jeghers syndrome gene, namely STK11, were found in primary melanoma." (PMID 39609109, 2025). "One hundred and seventy‐seven of these mutated genes, including Braf and Stk11 (Lkb1), were identified in mouse and human melanomas." (PMID 39115053, 2025). "STK11 can prevent melanoma cell invasion through the activation of the signal transducer and activator of STAT3/5 and FAK signaling pathways." (PMID 39609109, 2025). "STK11 (also known as LKB1 and PAR-4) encodes a serine/threonine kinase found in approximately 10% of melanomas." (PMID 31888295, 2019). "In keeping with published studies, there were frequent mutations of BRAF and NRAS in melanoma; BRAF, EGFR, KRAS, and STK11 in NSCLC; APC, BRAF, KRAS, and PIK3CA in CRC; KIT and PDGFR3A in GIST; and CTNNB1 in other tumours (desmoid fibromatosis)." (PMID 28196074, 2017). "Genes where a statistically significant difference in mutation rate was observed were APC (p = 9 × 10−7) in CRC, STK11 (p = 0.008) in NSCLC, and CDKN2A (p = 0.02), ERBB4 (p = 9 × 10−4), FLT3 (p = 0.02), and KDR (p = 0.01) in melanoma." (PMID 28196074, 2017). "This negative correlation of BRAF and STK11 at the protein level was also observed in our validation subset of BRAFV600E‐mutated human melanomas, supporting the notion of a lack of expression or low amounts of LKB1 in at least 50% of BRAFV600E‐mutated samples." (PMID 39115053, 2025). "Moreover, this compound activates AMPK in B16 melanoma cells through ROS-dependent STK11/LKB1 (serine/threonine kinase 11) activation." (PMID 36497321, 2022). "Mutations found in melanomas on the dorsal hand and foot were reported to be similar to those in melanomas at other sites of intermittently sun-damaged skin, whereas subungual and interdigital melanomas (n = 13) exhibited diverse mutations in PIK3CA, STK11, EGFR, FGFR3, and PTPN11." (PMID 36983205, 2023). "Such a ROS-induced repression of mTOR triggering autophagy was described in a melanoma cell line, whereby ATM activates AMPK via the AMPK kinase and ATM effector LKB1 (also known as STK11)." (PMID 28213588, 2017). "A study using melanoma cells has shown that the MAPK3/1 pathway phosphorylates STK11 on Ser325 and Ser428 and promotes the uncoupling of AMPK from STK11, which negatively regulates AMPK." (PMID 20808308, 2010). "STK11/LKB1 expression can be negatively regulated by hyper-methylation of the STK11 promoter region as demonstrated in clear cell renal carcinoma, colorectal cancer, or melanoma." (PMID 34831355, 2021).